NICN1 (nicolin 1, tubulin polyglutamylase complex subunit)
Synonyms: MGC12936
Tractability: PROTAC: ubiquitination databases record sites on it; its protein half-life has been measured.
Gene: Protein-coding gene on chromosome 3 (49,422,333 to 49,429,326, reverse strand). Ensembl gene ENSG00000145029.
Subcellular location: Nucleus
Subcellular location (Human Protein Atlas): Nucleoplasm
Pathways (Reactome):
Metabolism of proteins: Carboxyterminal post-translational modifications of tubulin
Gene Ontology:
Molecular function: protein binding
Cellular component: nucleoplasm; catalytic complex; microtubule; nucleus
Genetic constraint (gnomAD): Loss-of-function variants: 16 observed, 23.51 expected, observed/expected ratio (o/e) 0.68, 90% interval 0.46 to 1.03. The upper end of that interval is the gene's LOEUF score, 1.03, which puts it in group 4 of 6, group 1 being the genes least tolerant of losing a copy. Missense variants: 230 observed, 274.74 expected, observed/expected ratio (o/e) 0.84, 90% interval 0.75 to 0.93. Synonymous variants: 103 observed, 111.16 expected, observed/expected ratio (o/e) 0.93, 90% interval 0.79 to 1.09.
Homologues: Orthologues: chimpanzee NICN1 (99% identical), pig NICN1 (93% identical), macaque NICN1 (92% identical), guinea pig NICN1 (91% identical), rat Nicn1 (90% identical), mouse Nicn1 (89% identical), tropical clawed frog nicn1 (60% identical), zebrafish nicn1 (50% identical).
Diseases named in the same sentence as NICN1 in open-access papers:
NICN1 is named in the same sentence as 3 diseases in open-access papers, as found by Europe PMC text mining. Sharing a sentence is not in itself a finding about the gene and the disease. The quoted sentences say what the papers report.
glioma (1 paper, 2024). A benign or malignant brain and spinal cord tumor that arises from glial cells (astrocytes, oligodendrocytes, ependymal cells). "The results indicated that AMT, AS3MT, EGFR, NICN1, and POLR3K exhibited significant sex differences in expression within glioma tissues." (PMID 39722126, 2024).
nasopharyngeal carcinoma (1 paper, 2023). A carcinoma arising from the nasopharyngeal epithelium. "NICN1 is a tumor suppressor gene that has been shown to promote cell differentiation in a cell line derived from nasopharyngeal carcinomas; to date, little is known about the function of this gene in HPIs—a topic for future studies." (PMID 36757889, 2023).
NICN1 also shares sentences with these, for which no sentence is quoted: cancer (1 paper).